CFTR (CF transmembrane conductance regulator)
Diseases named in the same sentence as CFTR in open-access papers (continued):
Sharing a sentence is not in itself a finding about the gene and the disease.
cystic fibrosis (continued). "In cystic fibrosis bronchial epithelial (CFBE) airway cells, where all experiments were performed, our prior study demonstrated that PIAS4 overexpression increased the expression of both WT and F508del CFTR; for both proteins, its impact was greatest on the immature form, band B CFTR." (PMID 34764878, 2021). "TMEM16A is regarded as a secretory Cl− channel that might compensate for the absence of CFTR-mediated Cl− secretion in the airways of people with cystic fibrosis." (PMID 34360618, 2021). "Modulator drugs, which are “personalized” and that address discrete defects in the cystic fibrosis transmembrane conductance regulator (“CFTR”) protein, have transformed disease prognosis for some CF patients." (PMID 34067090, 2021). "The recent availability of cystic fibrosis transmembrane conductance regulator (CFTR) modulator therapies for people with CF has been heralded as transformative and is likely to change the future of CF disease trajectories." (PMID 33810202, 2021). "In contrast, another in vivo study could not confirm a protective effect of missing CFTR-function in cystic fibrosis for ADPKD." (PMID 34199520, 2021). "With the recent advances in cystic fibrosis transmembrane conductance regulator (CFTR) modulator therapies and the increased long-term survival rate of individuals with cystic fibrosis, this is a novel challenge emerging at the forefront of this disease." (PMID 32365523, 2020). "Commonly recognized non-pain examples include cystic fibrosis (CFTR Cl− channel), long QT syndrome types 1 and 2 (delayed K+ channel), long QT syndrome type 3 (Na+ channel), epilepsy (voltage-gated Ca++ channel), and diabetes mellitus (ATP-sensitive K+ channel)." (PMID 33987515, 2020). "Importantly, ECO derived from a cystic fibrosis patient showed no CFTR channel activity but normal chloride channel and MDR1 transporter activity." (PMID 33318612, 2020). "For example, CFTR, which detects no expression in primary hepatocytes in rats, was expressed at 5–10-fold higher levels in 3D structures, which resembled structures observed in patients with cystic fibrosis." (PMID 31565060, 2019). "If SLC268A is expressed in sperm from men with cystic fibrosis, it may partially compensate for the lack of CFTR during IVF." (PMID 31665287, 2019). "Cross-species comparative studies have highlighted differences between human and mouse cystic fibrosis transmembrane conductance regulator (CFTR), the epithelial Cl− channel defective in cystic fibrosis." (PMID 30969810, 2019). "In the Almaty region and Almaty city the pilot project for cystic fibrosis was started in 2017–2018 years with the algorithm–IRT, IRT, determine sweat chloride and CFTR genotyping." (PMID 33072949, 2018). "It is the most common fatal genetic disease in the developed world; 1 in 25–30 people with Caucasian ancestry carry a single defective copy of the CFTR gene and have no symptoms; 1 in ∼3000 babies are born with mutations on both alleles, resulting in the disease." (PMID 30538635, 2018). "This non-cystic fibrosis transmembrane conductance regulator (CFTR)-mediated, alternative chloride current has been discussed as an important modulator of disease and therapeutic target in CF patients." (PMID 29610986, 2018). "Despite the addition of cystic fibrosis transmembrane conductance regulator (CFTR) modulators to the cystic fibrosis treatment regimen, patients with CF continue to suffer from chronic bacterial infections that lead to progressive respiratory morbidity." (PMID 30459435, 2018). "Chronic lung disease resulting from dysfunctional cystic fibrosis transmembrane conductance regulator (CFTR) and NFκB-mediated neutrophilic-inflammation forms the basis of CF-related mortality." (PMID 29301535, 2018). "This was observed in both cystic fibrosis transmembrane conductance regulator (CFTR) null piglets and patients with CF, and furthermore was reversed by ivacaftor (CFTR potentiator) in patients with gating (G551D) mutations." (PMID 28916704, 2018).
cystic fibrosis (continued). "CFTR/Cystic Fibrosis is being returned by eMERGE but has not yet been evaluated by the ClinGen AWG." (PMID 30011878, 2018). "Since its discovery in 1989 cystic fibrosis transmembrane conductance regulator (CFTR) has been one of the most widely investigated proteins, presumably due to its central role in the common genetic disorder cystic fibrosis." (PMID 30618777, 2018). "On the opposite strand of the same position of chromosome 7 is the coding gene CFTR, a membrane protein that belongs to the ABC transporter family; it functions as a chloride/anion channel in epithelial cells around the body and is responsible for cystic fibrosis." (PMID 29140972, 2017). "Both mechanisms fail in CFTR−/− swine, suggesting that cystic fibrosis airways do not respond to inhaled pathogens, thus favoring infection and inflammation that may eventually lead to tissue remodeling and respiratory disease." (PMID 28983075, 2017). "This study demonstrates that there is a significant association between specific variants in CELF2, a gene encoding for a splicing factor involved in controlling the level of exon 9 skipping in CFTR, and risk of developing ARDS in children with pneumonia who do not suffer from cystic fibrosis." (PMID 27596159, 2016). "Breeding pairs of cftrtm1Eur [homozygous F508del-CFTR (FVB/129)] mice were obtained from the Erasmus MC, Rotterdam, The Netherlands, with the support of European Economic Community European Coordination Action for Research in Cystic Fibrosis EU FP6 LHHM-CT-2005-018932." (PMID 27895643, 2016). "Inhibition of CK2 closes CFTR wild type but not the cystic fibrosis mutant channel ∆F508-CFTR." (PMID 28009816, 2016). "Thus, in addition to possessing therapeutic potential for treating cystic fibrosis, antagonizing S1P/AMPK signaling may possess clinical utility for inflammatory pathologies that down-regulate CFTR." (PMID 26079370, 2015). "Patients having non-classic cystic fibrosis possess a minimum of a replica of a mutant gene which gives incomplete functioning of the CFTR gene, and the patients generally have no evident symptoms of improper digestion since some pancreatic exocrine functioning is preserved." (PMID 25850012, 2015). "We aimed to assess the efficacy of non-viral CFTR gene therapy in patients with cystic fibrosis." (PMID 26149841, 2015). "Currently, it is not clear how calumenin-CFTR interaction might contribute towards the observed pathophysiology of cystic fibrosis." (PMID 25120007, 2014). "ATF6 plays a major role in transcriptional repression of endogenous cystic fibrosis transmembrane conductance regulator (CFTR) under endoplasmic reticulum stress and is thought to be a potential therapeutic target for cystic fibrosis." (PMID 25241909, 2014). "While an increased prevalence of cystic fibrosis in patients with jejunal atresia and ileal atresia (JIA) has been described previously, it still may not be a practice routine to indicate a sweat test or DNA test for CFTR mutations in newborns presenting with JIA." (PMID 23217263, 2012). "Interestingly, CFTR, the cAMP Cl− gene responsible for cystic fibrosis, is not part of the human airway basal cell signature." (PMID 21572528, 2011). "Interestingly, CFTR, the cAMP-mediated Cl− ion channel, which is central to the pathogenesis of cystic fibrosis, was not expressed in the human airway basal cell signature." (PMID 21572528, 2011). "The CF gene, termed CFTR (cystic fibrosis transmembrane conductance regulator), is a chloride channel expressed on the apical side of the airway epithelial cells." (PMID 21994713, 2010). "Similar results were obtained in macrophages-like cells THP-1, epithelial cells of CF origin IB3-1 and their isogenic cells C38, corrected by insertion of cystic fibrosis transmembrane conductance regulator (CFTR)." (PMID 20037649, 2009).
cystic fibrosis (continued). "Besides abnormal CFTR localisation and expression in cystic fibrosis, also in non-cystic fibrosis airway tissue CFTR can be abnormally expressed in remodelled or dedifferentiated epithelium." (PMID 15967026, 2005). "Cystic fibrosis‐related diabetes (CFRD) is the most prevalent nonrespiratory complication of cystic fibrosis, with its prominence growing as survival rates improve due to advances in CFTR modulator therapies." (PMID 41552835, 2026). "CFTR modulators have revolutionized cystic fibrosis management by targeting the defective protein rather than its consequences." (PMID 41499328, 2026). "The introduction of the HEMT triple combo — elexacaftor/tezacaftor/ivacaftor (ETI) — which directly targets the defective cystic fibrosis transmembrane conductance regulator (CFTR) protein, has markedly improved clinical outcomes and quality of life in individuals with CF." (PMID 40705476, 2025). "Recent advances in therapies, including cystic fibrosis transmembrane conductance regulator (CFTR) modulator medications, have dramatically improved morbidity and mortality from CF, and the median expected age of survival in the CF population has increased significantly." (PMID 40558119, 2025). "Background/Objectives: Male infertility is a prevalent and often underrecognized manifestation of cystic fibrosis, primarily caused by congenital bilateral absence of the vas deferens (CBAVD) due to CFTR gene mutations." (PMID 41009940, 2025). "Highly-effective CFTR-modulator therapy with elexa-/teza-/ivacaftor (ETI) has led to improvements in pulmonary outcomes, sweat chloride, body mass index (BMI) and quality of life in people with cystic fibrosis." (PMID 38717689, 2024). "Despite the widespread distribution of the cystic fibrosis transmembrane conductance regulator (CFTR) along kidney tubules, specific renal phenotypes attributable to CF have not been well documented." (PMID 39170739, 2024). "Cystic Fibrosis (CF; OMIM: no 210700) is an autosomal recessive genetic disorder resulting from pathogenic variants in the CFTR (Cystic Fibrosis Transmembrane Regulator; at position 7q3.1) gene, which mainly affects White patients." (PMID 36832251, 2023). "Further study of cystic fibrosis lung disease and the origin of inflammation is not possible in humans and thus, CFTR knock-out pigs and ferrets have been engineered." (PMID 36927357, 2023). "However, following the widespread introduction of cystic fibrosis transmembrane conductance regulator (CFTR) modulators in 2019, the landscape of CF treatment has changed." (PMID 37881465, 2023). "This study has confirmed previous data also showing that infertile men with non-severe CFTR genotypes may develop mild, atypical forms of CF or CF-related disorders, may have undiagnosed Cystic Fibrosis, also as CF and CBAVD are partially overlapping disorders." (PMID 37510311, 2023). "One of the hallmarks of Cystic Fibrosis is high Chloride (Cl−) sweat concentration due to the absence of the CF Transmembrane conductance Regulator (CFTR) protein in the sweat acinus and collecting duct." (PMID 36751320, 2023). "Cystic fibrosis is a genetic condition in which the cystic fibrosis transmembrane conductance regulator channel (CFTR) is absent, has reduced function, or is nonfunctional (1, –, 4)." (PMID 37800950, 2023). "Multiple intra-intronic and intra-exonic mutations in CFTR (ABCC7), a gene closely related to ABCC8, have been associated with nonfunctional protein and cystic fibrosis disease." (PMID 33529173, 2021). "Cystic fibrosis is mainly related to secretory epithelia, such as sweat glands, airways, the pancreas, the gastrointestinal tract and vas deferens; however, the CFTR channels were also found in non-epithelial cells such as blood, the heart and the brain as well." (PMID 34832033, 2021).
cystic fibrosis (continued). "Cystic fibrosis transmembrane conductance regulator (CFTR)-regulated chloride channels are highly expressed in the gastrointestinal tract and when disrupted, as in CF, there is increased inflammation and cell turnover, which is believed to contribute to this increased risk." (PMID 33198722, 2020). "In contrast to healthy controls, CF tubuloids showed the characteristic lack of swelling after cystic fibrosis transmembrane conductance regulator (CFTR) activation by forskolin." (PMID 32466429, 2020). "Although rapidly becoming the standard of care in cystic fibrosis, current CFTR modulators do not treat all patients nor do they restore the rate of decline in lung function to normal levels." (PMID 32235608, 2020). "CF is defined by a lack of Cl− secretion through the cystic fibrosis transmembrane conductance regulator (CFTR) and an increased Na+ absorption mediated by the epithelial sodium channel (ENaC)." (PMID 32260534, 2020). "It is conceivable that dysfunction in cystic fibrosis transmembrane conductance regulator (CFTR) might be mechanistically involved in the chronic bronchitis seen in some smokers without COPD, thereby leading to a clinical phenotype similar to mild cystic fibrosis." (PMID 31354517, 2019). "Furthermore, HCO3‐ is indispensable for the antimicrobial function of the CF airway, and HCO3‐ transport can be regulated in normal human bronchial epithelial cells, however, in a cystic fibrosis transmembrane conductance regulator- (CFTR-) dependent fashion." (PMID 31080358, 2019). "Mutations in the cystic fibrosis transmembrane conductance regulator (CFTR) gene result in dysfunction or a lack of CFTR protein and impaired mucociliary clearance in CF patients." (PMID 30430043, 2018). "Currently there is no molecular treatment available for individuals with cystic fibrosis carrying nonsense or frameshift variants because such variants introduce a premature termination codon (PTC), and are not expected to produce CFTR protein." (PMID 30444886, 2018). "The defective function of the Cystic Fibrosis Transmembrane Conductance Regulator (CFTR) gene initiates a lifelong cycle of neutrophilic inflammation, progressive bronchiectasis, mucus obstruction and recurrent microbial infection of the CF airway." (PMID 30464745, 2018). "However, diabetes observed in cystic fibrosis is rather uncommon before the first decade, suggesting that CFTR is not of absolute necessity for GSIS but could represent a way to open Ano1 under some physiological conditions." (PMID 26582426, 2016). "The impact of SHSe on cystic fibrosis transmembrane conductance regulator (CFTR) function is also examined, as reduced CFTR function may be a pathophysiologic consequence of SHSe in CF and could modulate therapeutic interventions." (PMID 27754353, 2016). "The pathogenesis of CF-related inflammation and more specifically the role of the cystic fibrosis transmembrane conductance regulator (CFTR) in that respect are not entirely understood." (PMID 26549988, 2015). "In cystic fibrosis, the CFTR protein, which is expressed in epithelial cells, is not or only partially functional due to mutations in the Cystic Fibrosis Transmembrane Conductance Regulator (CFTR) gene." (PMID 24312174, 2013). "The consequences of defective cystic fibrosis transmembrane conductance regulator (CFTR) on epithelial cell function have been widely studied in the CF airway, but the effect on other cells is not as well documented." (PMID 24400140, 2013). "This could be in agreement with a lack of a kidney phenotype in cystic fibrosis patients, in which CFTR activity is compromised, but chloride intracellular concentration could be modulated by the plethora of chloride channels and transporters that are active in kidney cells." (PMID 23284854, 2012). "However, it is also expressed in other tissues which are not thought to be affected by cystic fibrosis and where the function of CFTR remains unclear, e.g. cardiac muscle and the kidney." (PMID 17883837, 2007).
cystic fibrosis (continued). "In cystic fibrosis, the lack of functioning CFTR impairs mucociliary and cough clearance, forming a nidus for infection and allowing organisms such as Pseudomonas aeruginosa (Ps." (PMID 15804356, 2005). "In the case of CF, CRS is classified as secondary, with its pathogenesis directly attributable to mutations in the CFTR gene Therefore, CRS, with or without nasal polyps, is a frequent comorbidity affecting both pediatric and adult people with cystic fibrosis (pwCF)." (PMID 41562847, 2026). "The identification and characterization of CFTR genevariants is carried out by the international Cystic FibrosisGenetic Analysis Consortium (CFGAC), which uniteslaboratories, the activities of which are aimed at geneticdiagnostics and research of CF around the world." (PMID 40297296, 2025). "Similarly, cystic fibrosis patients also experience skeletal muscle atrophy and dysfunction due to a lack of the CF transmembrane conductance regulator." (PMID 38860823, 2024). "Within CF pathology, sweat secretion remains unaltered by cholinergic agents, yet the secretion elicited via beta-adrenergic pathways is contingent upon cystic fibrosis transmembrane conductance regulator (CFTR) and is diminished or absent within the sweat glands of CF patients." (PMID 38611676, 2024). "The delivery of CFTR mRNA to mice lacking CFTR led to improvements in lung functional parameters, in a manner resembling FDA-approved cystic fibrosis drugs." (PMID 36678793, 2023). "Similar to human and pig cystic fibrosis cultures, FOXI1-KO and CFTR-KO ferret cultures failed to alkalinize the ASL following CFTR stimulation compared with wild-type cultures (P < 0.0001)." (PMID 37730992, 2023). "In contrast to cystic fibrosis macrophages, smoke-exposed THP-1 and AMΦ failed to augment phagocytosis in the presence of CFTR modulators." (PMID 31270372, 2019). "The cystic fibrosis transmembrane conductance regulator (CFTR) gene is an attractive target for gene editing approaches, which may yield novel therapeutic approaches for genetic diseases such as cystic fibrosis." (PMID 30893953, 2019). "Cystic Fibrosis Transmembrane Conductance Regulator (CFTR) is the secretory chloride/bicarbonate channel in airways and intestine that is activated through ATP binding and phosphorylation by protein kinase A, but fails to operate in cystic fibrosis." (PMID 28963502, 2017). "Moreover, in the transformed cystic fibrosis bronchial epithelial cell line CFBE41o-, the GC-induced increase of serum and GC dependent kinase 1 (SGK1) protein abundance enhanced ΔF508-CFTR and wildtype (wt) CFTR membrane expression by inhibiting their endocytic retrieval." (PMID 28825630, 2017). "A primary Cl− channel in respiratory epithelia responsible for proper MCC is the cystic fibrosis transmembrane conductance regulator (CFTR), which is dysfunctional or absent in cystic fibrosis – resulting in a significant reduction in the rate of MCC." (PMID 25117505, 2014). "A hypothetical approach to correcting the cystic fibrosis defect been proposed, based on downregulation of the E3 ligases RMA1 and CHIP, which enables mutant CFTR to complete its folding without being degraded." (PMID 25036888, 2014). "We therefore explored the hypotheses that glucose homeostasis is altered in CF airway epithelia and that elevation of glucose flux into ASL drives increased bacterial growth, with an effect over and above other cystic fibrosis transmembrane conductance regulator (CFTR)-related ASL abnormalities." (PMID 24124542, 2013). "It is now well established in cystic fibrosis that a lack of functional cystic fibrosis transmembrane conductance regulator (CFTR) impairs airway bicarbonate and fluid secretion producing an acidic, viscous ASL that is readily colonised by bacteria such as Pseudomonas aeruginosa." (PMID 24124542, 2013).
cystic fibrosis (continued). "In addition, regulation of immune activation, including TLR4 activation in alveolar macrophages and epithelial cells, appears to be dysregulated in CF patients, in part due to the lack of a functional cystic fibrosis transmembrane conductance regulator (CFTR) (26, –, 28)." (PMID 28947647, 2017).